HAND1 (heart and neural crest derivatives expressed 1)
Diseases named in the same sentence as HAND1 in open-access papers (continued):
Sharing a sentence is not in itself a finding about the gene and the disease.
schizophrenia (1 paper, 2024). A major psychotic disorder characterized by abnormalities in the perception or expression of reality. "In sum, HAND1::TCF3 target genes with neural-cardiac roles provide a means to elucidate the genetic causes of comorbidity between schizophrenia and cardiovascular diseases." (PMID 38167462, 2024). "HAND1 is critical for placenta development, which has been associated with the genetic risk of schizophrenia." (PMID 38167462, 2024). "The 105 schizophrenia-associated HC ELEs show strong enrichments of motifs recognized by POU3F3 and HAND1::TCF3 complex, all of which are relevant to schizophrenia." (PMID 38167462, 2024). "We identified 26 and 27 schizophrenia-associated HC ELEs containing POU3F3 and HAND1::TCF3-binding motifs respectively, further suggesting 86 unique putative target genes." (PMID 38167462, 2024). "Many putative target genes of schizophrenia-associated HC ELEs with the HAND1::TCF3-binding motif cause both neural and cardiac knockout mouse phenotypes and human Mendelian traits, likely due to the key role of HAND1 in heart development." (PMID 38167462, 2024).
stomach adenocarcinoma (1 paper, 2023). "To further determine the mechanism of HAND1 downregulation in GC, we analyzed the correlation between HAND1 expression and CpG methylation in TCGA stomach adenocarcinoma dataset using MEXPRESS." (PMID 36594085, 2023).
thyroid cancer (1 paper, 2023). "HAND1 has been reported to be downregulated and methylated in several cancers, including colorectal, pancreatic, small cell lung, ovarian and thyroid cancers, as well as melanoma 12-19, although the underlying mechanism studies are scanty." (PMID 36594085, 2023). "HAND1 expression is negatively regulated by the high-mobility group A1 (HMGA1) protein, and restoration of HAND1 expression leads to reduced growth of thyroid cancer cells." (PMID 36594085, 2023). "In thyroid cancer, HAND1 has been confirmed to be downregulated in differentiated and undifferentiated carcinomas, but expressed normally in benign neoplastic lesions and normal thyroid, and HAND1 restoration inhibits tumor cell growth." (PMID 36594085, 2023).
tumor (11 papers, 2016 to 2025). "Here, we show that HAND1 was frequently downregulated in GC by promoter methylation, and significantly correlated with tumor progression and poor prognosis of GC patients." (PMID 36594085, 2023). "HAND1 functions as a tumor suppressor that induces ER-stress-mediated apoptosis including UPR and mitochondrial apoptosis by targeting CHOP and BAK in GC cells." (PMID 36594085, 2023). "During this differentiation, an EC-intermediate step is skipped (no upregulation of SOX2) and a strong upregulation of germ layer differentiation markers, like AFP (also a yolk-sac tumor marker) and HAND1 was observed." (PMID 27283990, 2016). "However, the underlying mechanism of this phenomenon remains a challenge, necessitating further research on HAND1 as a potential tumour suppressor in various cancer types." (PMID 38689296, 2024). "In addition, we found that HAND1 restoration inhibited GC cell growth, proliferation and migration, suggesting that HAND1 does functions as a bona fide tumor suppressor in GC." (PMID 36594085, 2023). "The tumor-specific methylation of HAND1 promoter could be a candidate biomarker for GC." (PMID 36594085, 2023). "Moreover, HAND1(+) tumor cells express proliferative markers." (PMID 36291774, 2022). "It has been reported that overexpression of HAND1 attenuated tumor metastasis via downregulating β-catenin expression; thus, we hypothesized that Wnt/β-catenin signaling pathway may be involved in the effects of miR-196-5p/HAND1 axis on CCA behaviors." (PMID 35466323, 2022). "We performed transcription factor (TF) enrichment analysis on the identified key genes and found that TFs such as HAND1, RELA, and CLOCK were upregulated in the tumor margin, whereas members of the zinc finger family were predominantly upregulated in the tumor center." (PMID 40741331, 2025). "HAND1 regulates CHOP and BAK expression at the transcriptional level through interacting with CHOP, and further promotes GC tumor cells apoptosis and leads to tumor suppression." (PMID 36594085, 2023). "In order to study the expression patterns of genes in tumors and normal cell lines, PCR was used to detect the mRNA expression of genes, and the results showed that the expression of SPARCL1, HAND1, CLEC10A, PTGS1 genes in tumor group was significantly lower than that in the normal group." (PMID 35281077, 2022). "Additionally, RT-PCR also indicated the gene expression of iPSC-derived tumor tissue in three germ layers, demonstrating expressions of GATA4 in endoderm; HAND1 and GATA6 in mesoderm; and TUBB3, MAP2, and GFAP in ectoderm." (PMID 33224204, 2020). "Thus, HAND1 and BARX1 expression in tumor cells might determine prognosis and the need for adjuvant imatinib therapy because of shorter progression-free survival in such GIST." (PMID 36291774, 2022).
cancer (7 papers, 2013 to 2024). A tumor composed of atypical neoplastic, often pleomorphic cells that invade other tissues. "In several types of cancer, including colorectal, pancreatic, small cell lung, ovarian, thyroid, and melanoma, HAND1 is downregulated and methylated." (PMID 38689296, 2024). "Besides being involved in morphogenesis HMX2, like HAND1, is repressed in cancer and induction seems to be involved in inhibition of proliferation." (PMID 23969837, 2013). "The primary molecular abnormality in EBV associated LLC of the stomach is global and non-random CpG island methylation in the promoter region of many cancer-related genes (such as LOX, HRASLS, FLNC, HAND1, and THBD)." (PMID 24188515, 2013). "The subnetwork of hsa-let-7e retrieved from pan-cancer FFLs includes 57 target genes and 12 TFs including many cancer-related genes such as MYB, E2F2 and HAND1." (PMID 24205155, 2013).
cardiovascular disease (2 papers, 2023 to 2024). "According to previous reports, RELB, HAND1, and RELA are critical transcriptional factors in cardiovascular disease, and RELB and RELA have been confirmed to be related to AS progression." (PMID 37325477, 2023).
infection (1 paper, 2023). The state of being infected such as from the introduction of a foreign agent such as serum, vaccine, antigenic substance or organism. "At 0 h post-infection (control group), the upregulated proteins were enriched in function of cell development (through proteins such as HAND1 and CCN1); a pattern that was lost in the SARS-CoV-2 infected hiPSC-derived cardiomyocytes." (PMID 38087340, 2023).
HAND1 also shares sentences with these, for which no sentence is quoted: heart disease (3 papers); ventricular septal defect (2); bronchopulmonary dysplasia (1); cholangiocarcinoma (1); cognitive disorder (1); double outlet right ventricle (1); embryonal carcinoma (1); Hepatic steatosis (1); ischemia (1); melanoma (1); necrotizing enterocolitis (1); orofacial cleft (1); small cell lung carcinoma (1); steatosis (1); Ventricular arrhythmia (1).